RNU6-1054P (RNA, U6 small nuclear 1054, pseudogene)
Gene: Small nuclear RNA gene on chromosome 4 (118,606,450 to 118,606,553, forward strand). Ensembl gene ENSG00000223225.
Homologues: Orthologues: chimpanzee U6 (98% identical), macaque U6 (90% identical), pig U6 (83% identical), pig U6 (77% identical), dog U6 (76% identical). Paralogues in human: RNU6-1076P (99% identical), RNU6-1100P (99% identical), RNU6-1118P (99% identical), RNU6-1217P (99% identical), RNU6-355P (99% identical), RNU6-447P (99% identical), RNU6-785P (99% identical), RNU6-791P (99% identical), RNU6-860P (99% identical), U6 (99% identical), RNU6-1199P (98% identical), RNU6-1319P (98% identical), and 1289 more.